STAT1 (signal transducer and activator of transcription 1)
Diseases named in the same sentence as STAT1 in open-access papers (continued):
Sharing a sentence is not in itself a finding about the gene and the disease.
tumor (continued). "IFNγ then send signals via STAT1 to increase anti-tumor responses through the activation of natural killer cells, macrophages and CD8+ T cell-mediated cytolytic activity." (PMID 25076205, 2014). "While STAT1 can act as a tumor suppressor, an oncogenic potential of STAT1 has been shown in certain cellular contexts." (PMID 24810717, 2014). "Pulverized tumor tissue obtained from the same patients was analyzed for STAT1 mRNA and protein by RT-PCR and western blotting." (PMID 24725474, 2014). "Correlating with our clinical observations, our in-vitro studies have provided further support that STAT1 carries tumor suppressor functions in ESCC." (PMID 25355139, 2014). "Interestingly, a number of genes that change their expression in immortalized cells, e.g. PI3K, MDM2, SMAD2/3 and STAT1, are implicated in the evasion of apoptosis and acquisition of insensitivity to growth-inhibiting signals, which are characteristic features of tumour cells." (PMID 24371281, 2014). "We demonstrated that activation of fibroblasts with TNF, a cytokine with a central role in the pathogenesis CD, is sufficient to reduce their ability to induce STAT1 signaling in tumor cells." (PMID 24818101, 2014). "We found that STAT1 expression inversely correlated with the depth of tumor invasion and tumor size (p = 0.047 and p = 0.029, respectively, Chi square)." (PMID 25355139, 2014). "STAT1 appears to exert its tumor suppressor functions via multiple mechanisms, including downregulation of caspases, Fas, FasL, TRAIL and p21waf1." (PMID 25355139, 2014). "STAT1 has been described as a tumor suppressor because of its function as a mediator of IFN-γ - dependent immunosurveillance." (PMID 24725474, 2014). "Although the role of STAT1 in tumorigenesis appears to be complex, these findings demonstrate that STAT1 can act as an inhibitor of tumor progression by restraining tumor growth and metastasis." (PMID 24818101, 2014). "18Co cells did not impact the activity of NFκB, Wnt, AP1-driven signaling pathways, however, we showed that fibroblasts – in a dose-dependent manner – enhanced STAT1-driven transcriptional activation in tumor cells." (PMID 24818101, 2014). "For example, when the pooled tumor samples were compared against pooled normal samples, only two TFs (Stat1 and Stat2) were identified." (PMID 23885756, 2013). "Activated STAT1 induces anti-proliferative and pro-apoptotic genes that directly hamper tumor growth." (PMID 23950841, 2013). "Stat1 immunohistochemistry of untreated MMTV-PyMT adenocarcinomas identified sub-populations of Stat1-positive tumor cells." (PMID 23520493, 2013). "Our results indicate that Stat1 and Stat2 are significantly more active (i.e. their target genes tend to be more highly expressed) in tumor cells than normal cells." (PMID 23885756, 2013). "At the mRNA level, we found that expression of Stat1 was significantly reduced in tumor cells compared to normal breast tissues (P=2e-8, t-test)." (PMID 23885756, 2013). "Another STAT family member, STAT1, possesses cancer-inhibitory properties and can promote apoptosis in tumor cells upon activation." (PMID 23950841, 2013). "In contrast, STAT1, which was up-regulated with tumor progression in our study, showed a further increase in expression after chemotherapy." (PMID 23451142, 2013). "The cutoff value for the density of CD8, CD20, and CD33+/p-STAT1+ groups was 28, 34, and 11 cells, respectively, per high-powered field in the center of the tumor." (PMID 23307253, 2013). "We previously demonstrated that IL-27 inhibits the tumor growth of B16F10-WSX-1 cells through the WSX-1/STAT1 and IRF-1 pathway." (PMID 24155891, 2013). "Depletion of SOCS1 negatively affects various tumor types like melanoma and neuroendocrine tumors supporting an oncogenic potential for the STAT1 inhibitor SOCS1." (PMID 24058673, 2013). "We collected tumor lysates at days 1, 3, 5, and 7 after chemotherapy and blotted for Stat1 and p-Stat1, -3, and -5 proteins." (PMID 23520493, 2013).
tumor (continued). "Studies have shown tumor escape mechanisms in STAT-1−/− mice, and STAT-3 signaling was identified in the inhibitory effects of IL-10 on DC maturation and migration, and impairment of CD4+ T-cell function." (PMID 24216992, 2013). "This suggested that Stat1 positive tumor cells, which pre-existed in untreated tumors, were inherently resistant to DNA-damaging agents, as reported." (PMID 23520493, 2013). "Many experimental data have shown that high expression of IFN-induced genes, including STAT1 itself, promotes tumour growth, metastasis, and resistance to chemotherapy and radiation." (PMID 24065129, 2013). "While STAT1 increases the rates of apoptosis, improves functioning of the immune system and functions as a tumor suppressor by reducing cancer proliferation, STAT3 maintains the malignant transformation by increasing the proliferation of tumors." (PMID 23708675, 2013). "IL-18 was proposed to have a role in IFN-γ mediated activation of STAT1, which is known to have a role in tumor suppression." (PMID 24273542, 2013). "In contrast to the tumor suppressor function of activated STAT1, STAT3 is mainly identified as an oncogene." (PMID 23825585, 2013). "Activated STAT1 signaling has tumor suppressive roles by inhibiting angiogenesis, tumor growth and metastasis as well as promoting apoptosis." (PMID 24274066, 2013). "STAT1 is also known to act as a negative regulator of tumor growth and metastasis by playing a key role in the inhibition of angiogenesis." (PMID 23950841, 2013). "It is unclear, however, if the possible tumor-promoting activity of KPNA2 is due to its function as a nuclear transporter for selective immunoregulatory proteins such as STAT1 and interferon-γ-induced transcription factor IRF-1." (PMID 23536776, 2013). "Stat1 was significantly up-regulated in a DNA-damage-resistant population of residual tumor cells, and a pre-existing Stat1 sub-population was identified in untreated tumors." (PMID 23520493, 2013). "It should be noted, however, that in certain cellular contexts STAT1 has been found to be a tumor promoter." (PMID 22423663, 2012). "Wilcoxon signed rank test was used to compare STAT1 intensity levels in tumor samples and adjacent normal breast tissues." (PMID 22264274, 2012). "In the endocrine treatment experiment, nu/nu mice or STAT1-/- mice were transplanted with 106 SSM3 tumor cells or tumor fragments, respectively." (PMID 22264274, 2012). "In contrast, STAT1 expression was highly variable among tumor samples, consistent with previous reports." (PMID 22264274, 2012). "In contrast, STAT1 expression is elevated in epithelial cells of normal breast tissues adjacent to the malignant lesions, suggesting that STAT1 is selectively downregulated in the tumor cells during tumor progression." (PMID 22264274, 2012). "Several miR-143 targets, including DNMT3A and KRAS, and miR-145 targets including BNIP3, IRS, C-MYC, YES and STAT1, have been identified, indicating that miR-143 and 145 act as tumor suppressors to repress tumor proliferation or promote apoptosis." (PMID 22438992, 2012). "While elucidating the roles of pregnancy-associated hormones in mammary tumorigenesis will be the target for future investigation, work investigating the mechanism by which STAT1 suppresses tumor formation has begun." (PMID 22264274, 2012). "The clinical implication of these findings is that caution should be taken in interpreting the involvement of STAT1 in treatment outcomes when STAT1 activation signature in whole-tumor biopsies is used as a prognostic indicator." (PMID 22264274, 2012).
tumor (continued). "Thirty-four percent of the tumor cases (54 out of 161) exhibited low STAT1 staining in the neoplastic cells, whereas 37% and 29% showed intermediate and high staining, respectively." (PMID 22264274, 2012). "STAT1 enhances inflammation and innate and adaptive immunity, triggering in most instances anti-proliferative and pro-apoptotic responses in tumor cells." (PMID 22863767, 2012). "Since Stat1 and Stat3 are often expressed simultaneously in the same tumor cells, it has been suggested that one protein dominates over the other in the influence on survival, depending on e.g. the durability of activation of each protein." (PMID 22838736, 2012). "Overall, our data show that HDACi enhances IRF-8 expression in tumor cells involving STAT1, and promotes Fas-mediated killing and antitumor activity via an IRF8-dependent pathway." (PMID 23028998, 2012). "Despite its major role as a tumor antagonist, STAT1 can also have functions in cancer cells, as documented in mouse leukemia." (PMID 22423663, 2012). "It has also been reported that HDACi, such as TSA, alters the expression of IFN-γ-inducible genes through acetylation of STAT1 in myeloid cells and tumor cells." (PMID 23028998, 2012). "In the reverse experiment, 3/27 Stat1−/− tumors evolved in Stat1+/+ mice, translating into a 30% tumor incidence after adjustment for the significantly lower transplantation success rate." (PMID 22185785, 2011). "Our studies indicate that autophagy activation in tumor cells from the mice treated prophylactically with the TLR4/9 agonist complex is associated with the elevated levels of IFNγ expression and STAT1 phosphorylation." (PMID 21931823, 2011). "STAT1 has been considered generally to be a tumour suppressor, while STAT3 and STAT5 are known to be proto-oncogenes." (PMID 21338529, 2011). "The signal transducer and activator of transcription 1 (STAT1) plays a critical role in carcinogenesis by mediating various biological responses and has been implicated as a tumor suppressor." (PMID 21625390, 2011). "Tumor incidence increases upon transplantation of Stat1−/− mammary glands into Stat1+/+ recipients compared to a Stat1+/+ => Stat1+/+ scenario (30% versus 11%)." (PMID 22185785, 2011). "Using different mouse models, both groups concluded that STAT1 suppresses ERBB2/neu/HER2 tumor formation." (PMID 22185785, 2011). "Meanwhile, STAT1-deficient mice displayed an increase in Th2 polarization due to the block in IFN-γ signaling, and were more susceptible to tumor development." (PMID 21943203, 2011). "After activation, STAT1 regulates the expression of genes that promote growth arrest and apoptosis, and is considered as a putative tumour suppressor." (PMID 21694723, 2011). "By crossing Stat1fl/fl mice with MMTV-neu-IRES-cre mice, Klover et. al. showed that tumor onset is significantly accelerated in Stat1fl/fl × MMTV-neu-IRES-cre mice compared to STAT1-expressing wild-type controls." (PMID 22185785, 2011). "In summary, our observations enable us to conclude that STAT1 suppresses tumor formation in the mammary epithelial cells themselves." (PMID 22185785, 2011). "Experimental and computational data together suggest that the tumor cells are less responsive to IFNγ in that they require higher doses of the cytokine for efficient STAT1 activation and growth inhibition." (PMID 21310022, 2011). "To control for tumor onset provoked by the transplantation procedure itself, we additionally transplanted Stat1+/+ mammary tissue into Stat1+/+ mice." (PMID 22185785, 2011). "It is also known that IFN-γ/STAT1 signaling on host immune cells is essential for the development of anti-tumor lytic effecter cells." (PMID 21124930, 2010). "In this scenario, while adequate levels of STAT1 are pivotal for the establishment of IFNα effects, low levels or overexpression of this transcription factor seems to be advantageous for tumor cells." (PMID 21234393, 2010).
tumor (continued). "In the BRCA1-wild type cells, functional BRCA1, as a tumor suppressor, acts in concert with STAT1 to activate transcription of a subset of IFN-γ gene targets and growth inhibition by cytokine." (PMID 20576130, 2010). "For example, tumor cell lines with defects in STAT1, IRF9 and Jak1 have been identified and have been found to have reduced in vitro responsiveness to IFN-α." (PMID 20398276, 2010). "We were then able to identify relationships between expression levels of the IFN/STAT1 pathway, resistance of tumor clones to cytotoxic agents, and the ability of tumor clones to colonize lungs." (PMID 19503789, 2009). "We conclude that on the transcriptional level, STAT1 contributes to regulation of the Warburg effect, which reflects the dependence of tumour cells on glycolysis as a major pathway of energy production necessary for tumour growth." (PMID 19891767, 2009). "STAT1 knockdown completely reversed the tumor phenotype, significantly reducing lung colonization while significantly increasing sensitivity to Dox." (PMID 19503789, 2009). "We found that IR treatment resulted in modest suppression of GG, CC and OP gene and protein expression in STAT1 WT tumours." (PMID 19891767, 2009). "We also showed that selection of the sensitive parental tumor SCC61 against IFNα or IFNγ led to constitutive overexpression of the IFN/STAT1 pathway and development of resistance to IR." (PMID 19503789, 2009). "To define a cut-off expression level to delineate high and low expressors of the IFN/STAT1 pathway we developed a method for rapid and efficient screening of cell lines and tumor clones." (PMID 19503789, 2009). "While STAT1 has traditionally been regarded as pro-apoptotic and tumour-suppressing, we previously demonstrated that over-expression of the STAT1 pathway confers radio resistance and IFN-resistance." (PMID 19891767, 2009). "This score was calculated as an average of the log2-transformed expression value for each of the five marker genes and was used to estimate the IFN/STAT1 pathway expression level in experimental cell lines and tumor clones." (PMID 19503789, 2009). "Of these pathways, GG had the most concordant changes in gene and protein expression and demonstrated a STAT1-dependent expression of genes and proteins consistent with tumour-specific glycolysis." (PMID 19891767, 2009). "We compared gene and protein expression profiles of untreated STAT1 WT and KD tumours and identified the differential expression of 92 genes and 266 proteins." (PMID 19891767, 2009). "In contrast to Stat3, Stat1 is anti-oncogenic; it is a potent inhibitor of tumor growth and promoter of apoptosis." (PMID 19274102, 2009). "Recent reports and our current observations strongly suggest that STAT1 provides a promising target for sensitization of primary tumors and perhaps distant metastasis to anti-tumor therapy." (PMID 19503789, 2009). "In our previous reports we demonstrated that the nu61 tumour, selected from the SCC61 tumour by in vivo fractionated irradiation, is more radioresistant based on in vivo assays and overexpresses Stat1." (PMID 19437244, 2009). "While Stat3 contributes to oncogenesis, in part, through inhibition of apoptosis, Stat1 is anti-oncogenic; it mediates the apoptotic effects of interferons and contributes to tumor immunity." (PMID 19274102, 2009). "Here we report that tumor cells that constitutively overexpress the IFN/STAT1 pathway, and are thus resistant to the cytotoxic effects of this pathway, are preferentially selected for colonization by the lung microenvironment." (PMID 19503789, 2009). "Knockdown of STAT1 led to significant growth suppression in untreated tumours and radio sensitization of irradiated tumours." (PMID 19891767, 2009). "Tumor cells that constitutively overexpress the IFN/STAT1 pathway (STAT1H genotype) are selected by the lung microenvironment." (PMID 19503789, 2009).
tumor (continued). "To investigate the mechanisms by which STAT1 confers an aggressive tumour phenotype, we characterized the downstream pathways regulated by STAT1." (PMID 19891767, 2009). "KD of STAT1 in irradiated tumours significantly (t-test; P = 0.017) suppressed tumour volume at day 68 by 6.5-fold." (PMID 19891767, 2009). "We previously reported that selection of the radioresistant tumor nu61 by in vivo fractionated IR was accompanied by overexpression of the IFN/STAT1 pathway and combined resistance to IR, IFNα, and IFNγ." (PMID 19503789, 2009). "We found that STAT1 WT tumours demonstrated significant protection (t-test; P < 0.0001) from IR-induced suppression of energy pathways relative to STAT1 KD tumours." (PMID 19891767, 2009). "An interferon gene signature was also present in the profiles derived from the tumor epithelium of the ER-positive tumors (e.g., STAT1, IFIT1, IFIH1, IFI27, ISG15, OAS1, OAS3, OASL) and ER-negative tumors (e.g., HLA-DQA1 and HLA-DQB1)." (PMID 19225562, 2009). "We demonstrate the pre-existence of clones in the B16F1 tumor cell population that overexpress the IFN/STAT1 pathway." (PMID 19503789, 2009). "Previously, we showed that stable knockdown of STAT1 in IR-resistant and IFNα/IFNγ-resistant tumor cells led to radiosensitization, suggesting that STAT1 is one important mediator in the IR-resistant tumor phenotype." (PMID 19503789, 2009). "Traditionally IFN/STAT1 signaling is connected with an anti-viral response and pro-apoptotic tumor-suppressor functions." (PMID 19503789, 2009). "First, the STAT1-dependent development of tumor clones with an increased propensity for lung colonization and resistance to IFNγ is associated with the development of resistance to Dox." (PMID 19503789, 2009). "We performed pair-wise comparisons of STAT1 WT and KD tumours for untreated and irradiated conditions and identified differentially expressed genes and proteins belonging to the GG, CC and OP pathways." (PMID 19891767, 2009). "Given that phosphorylation is essential for Stat1 activation, detection of phosphorylated Stat1 in human tumors appears to be inconsistent with its anti-proliferative and tumor suppressor activities." (PMID 18941537, 2008). "That is, tumor growth after subcutaneous injection of the MEFs in nude mice was significantly enhanced for MEFs reconstituted with either Stat1 WT or Stat1S727A and treated with shRNA against p27Kip1." (PMID 18941537, 2008). "It is of interest that tumor growth of Ras-transformed MEFs in nude mice is more highly suppressed by Stat1S727A than Stat1 WT." (PMID 18941537, 2008). "Although increased expression of STAT1 has been observed in many human neoplasia, this molecule can be considered a potential tumor suppressor, since it plays an important role in growth arrest and in promoting apoptosis." (PMID 18179710, 2008). "STAT1 plays a prominent role in the effector immune response, whereas STAT3 is implicated in tumor progression and down-regulation of the response to type I IFNs." (PMID 18954464, 2008). "The tumor suppressor properties of Stat1 in Ras transformation are reversed by the inactivation of p27Kip1." (PMID 18941537, 2008). "Our approach with shRNA clearly demonstrated that the anti-tumor activity of Stat1 is dependent on p27Kip1." (PMID 18941537, 2008). "Our findings suggest a different regulation of the anti-tumor activity of Stat1 by site-specific phosphorylation." (PMID 18941537, 2008). "Consistent with tumor growth, we detected a higher amount of phosphorylated Erk1/2 in Stat1−/− than in Stat1+/+ lung tumors, which indicated the induction of the Ras-MAPK pathway by activated K-Ras." (PMID 18941537, 2008). "The effects of Stat1 are not confined to Ras-transformed MEFs only since activation of the K-Ras pathway in lung tissue by urethane results in a higher tumor incidence in Stat1−/− than in Stat1+/+ mice." (PMID 18941537, 2008).